TNF (tumor necrosis factor)
Diseases named in the same sentence as TNF in open-access papers (continued):
Sharing a sentence is not in itself a finding about the gene and the disease.
tuberculous pleurisy (14 papers, 2009 to 2024). "Meanwhile, with a cut off of 30.3(ng/L), the sensitivity and specificity of TNF-α for tuberculous pleurisy diagnosis were determined to be the highest, 83% and 97% respectively, which is in agreement of previous findings." (PMID 24984978, 2014). "Pleural fluid TNF-α level also proved to be useful in prognosticating tuberculous pleurisy with high sensitivity and specificity rates." (PMID 24244502, 2013). "Some studies of tuberculous pleurisy have reported elevated levels of TNF at the site of infection." (PMID 38835752, 2024). "In addition, CD4+ T cells expressing different combinations of IFN-γ, IL-2, TNF-α, IL-17A, and IL-22 have been described in tuberculous pleurisy." (PMID 23451159, 2013). "Chen and co-workers reported that TNF-α induced MMP-9 synthesis in human pleural mesothelial cells associated with Mycobacterium tuberculosis infection and that this process might be implicated in the pathogenesis of tuberculous pleuritis." (PMID 30544870, 2018). "A recent study showed that EspC as an immunodiagnosis antigen also induced cytokine production of TNF-α, IL-6, and IFN-γ of pleural fluid mononuclear cells (PFMCs) from patients with tuberculous pleuritis (TBP)." (PMID 31134163, 2019). "IL-1β, IL-2, IL-6, TNF-α, PAI-1, and t-PA levels in pleural fluids of 40 patients with tuberculous pleurisy and 38 patients with tuberculous empyema were measured." (PMID 27034588, 2016). "Tumor necrosis factor (TNF)-α and matrix metalloproteinases (MMPs) are elevated in pleural fluids of tuberculous pleuritis (TBP) where pleural mesothelial cells (PMCs) conduct the first-line defense against Mycobacterium tuberculosis (MTB)." (PMID 26367274, 2015). "However, following stimulation with MTB-specific peptides of ESAT-6/CFP-10, CD4+CD69+ T cells from the same patients with tuberculous pleurisy expressed high levels of IFN-γ, IL-2 and TNF-α, indicating that the response was MTB-specific." (PMID 21887301, 2011).
uterine fibroids (14 papers, 2007 to 2025). "According to a large amount of data, TNF-α also seems to be an extremely important cytokine in the biology of uterine fibroids, associated symptoms and conditions." (PMID 37305407, 2023). "Inflammatory factors, such as TNF-a, have been isolated at higher levels in individuals with uterine leiomyomas, highlighting the strong association between inflammation and uterine leiomyomas." (PMID 36771423, 2023). "This study will explore the association between tumor necrosis factor α (TNF-α) and uterine fibroids (UFs)." (PMID 32872031, 2020). "Inflammation plays a critical role in the development of uterine fibroids, characterized by elevated expression levels of pro-inflammatory and inflammatory cytokines such as interleukin-1, interleukin-6, interleukin-10, TNF-α, and TGF-β." (PMID 39911698, 2025). "Currently available data suggest the occurrence of an inflammation-like condition in women with uterine fibroids, with TNF-α being a strong inducer of the state." (PMID 37305407, 2023). "At the same time, some studies have shown that the Biejiajian pill can inhibit the expression of TNF-α to inhibit the growth of uterine fibroids." (PMID 35845578, 2022). "We observed multiple deregulated signaling pathways, including those for IGF-1, neuregulin, mTOR, TGFB1, CTNNB1, and TNF, in the mouse uterine leiomyomas." (PMID 33244099, 2020). "TNF-α is related to the occurrence of uterine fibroids, which may be due to the inhibition of the immune state of the body." (PMID 35845578, 2022). "Notably, the treatment of the myometrium with TNF increases the transcriptional activity of activin A, a pro-fibrotic marker highly expressed in uterine leiomyomas." (PMID 34298942, 2021). "They demonstrated that coculture of adipocytes and uterine leiomyoma cells results in an increased proliferation of leiomyoma cells, and they have also demonstrated that TNF-α treatment increases human uterine leiomyoma cells proliferation in a concentration-dependent manner." (PMID 24163697, 2013). "Both primary and secondary TFI groups showed significantly elevated levels of TNF-α, IL-8, IL-6, and TGF-β1 in the peritoneal fluid as compared to patients with uterine fibroids." (PMID 33092547, 2020). "Human uterine leiomyoma (HuLM) cells responded more to leptin treatment compared to myometrium cells with increased secretion of inflammatory factors: IFNγ, IL-6, IL-8, MCP-1, GM-CSF, and TNF-a." (PMID 36771423, 2023). "Among these molecules, the inflammation mediator TNF-α and the growth factors activin A and TGF-β can be considered the most important ones because they are known to be involved in the fibrosis that characterizes the uterine fibroids." (PMID 33922329, 2021). "The results of the present study revealed that the serum levels of TNF-α, IL-8, IL-6, and TGF-β1 were higher in the secondary group than in the uterine fibroids group, and the differences in the levels of TNF-α, IL-6, IL-8 and TGF-β1 in serum between these two groups were statistically significant." (PMID 33092547, 2020). "Compared to the patients with uterine fibroids, patients with secondary TFI showed significantly higher levels of TNF-α, IL-8, IL-6, and TGF-β1 in the serum samples, whereas the serum cytokine concentrations were not statistically significant between patients with primary TFI and the control group." (PMID 33092547, 2020).
vitamin B12 deficiency (14 papers, 2011 to 2025). A disease characterized by low serum levels of vitamin B12, either inherited or acquired. "Vitamin B12 deficiency increased plasma triglycerides, cholesterol and pro-inflammatory markers (such as tumor necrosis factor-alpha, interleukin-1 b and interleukin-6), as well as decreased adiponectin concentrations in mice." (PMID 39010125, 2024). "Vitamin B12 deficiency can lead to the upregulation of the cytokine TNF-α and has been linked to multiple perinatal disorders including pre-eclampsia and neonate growth retardation." (PMID 38612969, 2024). "Vitamin B12 deficiency contributes to a higher degree of inflammation in mice due to the over-expression of pro-inflammatory cytokines like TNF-α." (PMID 37664383, 2023). "TNF-α is a hallmark of inflammation and several lines of evidence suggest the association of vitamin B12 deficiency with an increased incidence of inflammation and associated metabolic complications." (PMID 27608037, 2016). "Additionally, vitamin B12 deficiency can further lead to myelin damage by increasing levels of neurotoxic cytokines such as tumor necrosis factor-alpha (TNF-alpha) and decreasing neurotrophic cytokines such as interleukin-6 (IL-6)." (PMID 40083591, 2025). "- Vitamin B12 deficiency contributes to a higher degree of inflammation in mice due to the over-expression of pro-inflammatory cytokines like TNF-α. - Vitamin B supplements increased Actinobacteria, Odoribacteraceae and decreased Campylobacteraceae, Fusobacteriaceae, and Prevotellaceae." (PMID 37664383, 2023). "Thus, studies assessing the relationship between GPA, IFA, TNF-α, IL-6 as well as cardiometabolic risk factors and vitamin B12 deficiency among metformin-treated T2DM patients are warranted." (PMID 33784336, 2021). "Thus, GPA, IF and TNF-α are independent risk factors associated with vitamin B12 deficiency among metformin-treated T2DM." (PMID 33784336, 2021). "Another thing is that the abnormal conditions affecting balance between IL-6 and TNF-α in the CNS may cause cobalamin deficiency, which leads to demyelination." (PMID 26435864, 2015). "Participants with vitamin B12 deficiency had significantly higher levels of IFA, GPA, TNF-α, TC, LDL and albumin compared to those with normal vitamin B12 levels (p < 0.05)." (PMID 33784336, 2021). "This deregulation of the balance between TNF-α and EGF synthesis induced by cobalamin deficiency has been verified in the sera of patients with pernicious anemia and in the cerebrospinal fluid of SCD patients." (PMID 26435864, 2015). "This deregulation of the balance between TNF-α and EGF synthesis is induced by cobalamin deficiency." (PMID 21524288, 2011). "Neuropathological lesions in SACD have been found to be due to overproduction of the myelinolytic Tumor necrosis factor α (TNFα) and to the reduced synthesis of the two neurotrophic agents; the Epidermal growth factor (EGF) and interleukin-6 caused by vitamin B12 deficiency." (PMID 26385097, 2015).
bronchiolitis (13 papers, 2010 to 2025). Inflammation of the bronchioles characterized by swelling of the bronchioles and mucus accumulation. "Some studies in children have implicated TNF-α in the pathogenesis of RSV-induced bronchiolitis, but direct evidence of TNF signaling pathway in the pathogenesis of wheezing and bronchoconstriction has not been demonstrated." (PMID 33080861, 2020). "We used ELISA to detect IL-4, IL-5, TNF-α, and IgE in the serum of children in both groups, and the results suggested that IL-4, IL-5, TNF-α, and IgE were significantly elevated in children with bronchiolitis compared with healthy children." (PMID 37389334, 2023). "Plasma level of TNF-α, which originates from Th1 cytokine, has been reported to be of great significance in predicting the development of recurrent wheezing during acute bronchiolitis." (PMID 33691633, 2021). "Both findings implicate impaired early innate immune response in infants with RSV-bronchiolitis linked to lower TLR8 expression and subsequent lower TNF-α release, that has been associated with acute RSV infection." (PMID 20946625, 2010). "Similarly, proteins involved in NFkB pathway signaling such as TNF, the Tnf receptor, IKK, and others (green) were all predicted targets of sRNAs associated with RV-only bronchiolitis, leading to their predicted downregulation." (PMID 38410509, 2024). "In addition, TNF-α overexpression in type II AECs led to increased septal destruction, bronchiolitis, pulmonary inflammation, and PH." (PMID 33537342, 2020). "Genetic polymorphisms of SFTPA (surfactant protein A), SFTPD (surfactant protein D), TLR (toll like receptor) 4, TNF (tumor necrosis factor), IL4 (interleukin 4), IL9, IL10, IL8, IL13, IL4RA, and CCL5 have been reportedly associated with a susceptibility to RSV-induced bronchiolitis." (PMID 23986756, 2013). "In this study, we primarily found that the MUC1 protein levels, as well as TNF-α levels, were significantly up-regulated in the sputum of children with RSV-infected bronchiolitis during the exacerbation period." (PMID 38036963, 2023). "Pro-inflammatory cytokines IL1β, IL6, TNFα, IL18 and IL23 were increased in the bronchiolitis samples relative to their respective control cohort." (PMID 36561744, 2022). "Here we show that elevated levels of pro-inflammatory cytokines (IL1β, IL6, TNFα, IL18, IL23), regulatory cytokines (IL10, IL17A) and IFNγ were found in the three bronchiolitis cohorts." (PMID 36561744, 2022).
bronchitis (13 papers, 2013 to 2025). An acute or chronic inflammatory process affecting the bronchi. "On the other hand, two TNF-α SNPs (rs1800630 and rs1800629) were exclusively associated with bronchitis within the Greenlandic population." (PMID 28740106, 2017). "In Greenland, the Inuit with genotype GA of TNF-α rs1800629 had a significantly higher prevalence of bronchitis (38.9%) than that in GG (25.4%)." (PMID 28740106, 2017). "Using the sensitivity analysis, we further revealed the significant associations of LT-α rs909253 and rs1041981 with bronchitis in Danish Inuit, while the association of TNF-α rs1800630 with bronchitis did not remain significant." (PMID 28740106, 2017). "Significant differences in the prevalence and risk of bronchitis were found in genotypes of LT-α and TNF-α, but not in ALOX5, LTC4S, TBXA2R, ADAM33, NOS1 and ORMDL3 in the Inuit populations residing both in Greenland and in Denmark." (PMID 28740106, 2017). "These factors induce the release of pro-inflammatory cytokines, such as interleukin-6 (IL-6) and tumor necrosis factor-alpha (TNF-α), amplifying airway inflammation and increasing the likelihood of bronchospasm, laryngospasm, and other RAEs." (PMID 41465940, 2025). "In line with the protein estimation, the untreated positive control group showed a significant elevation of TNF-α concentrations in the BALF compared to the normal control (p<0.01), indicating induced bronchitis." (PMID 24106676, 2013).
cerebral toxoplasmosis (13 papers, 2010 to 2025). Infections of the brain caused by the protozoan toxoplasma gondii that primarily arise in individuals with immunologic deficiency syndromes (see also aids-related opportunistic infections). "Since some cytokines such as IFN-γ, TNF, and IL-12 are key factors for the control T. gondii in mice, a high risk for severe primary or reactivated cerebral toxoplasmosis might be expected in patients with primary deficiency for these cytokines and their receptors." (PMID 30873157, 2019). "Here we present a 74-year-old woman who developed fatal cerebral toxoplasmosis after anti-tumor necrosis factor-α (TNF-α)." (PMID 39959486, 2025). "We previously showed that Ly6Chi monocytes express TNF and IL-10 in the CNS during cerebral toxoplasmosis." (PMID 28680853, 2017). "Clinical cases of cerebral toxoplasmosis and chorioretinitis have been reported in RA patients undergoing treatment with TNF-α antagonists." (PMID 29065914, 2017). "In cerebral toxoplasmosis, TNF-α acts synergistically with IFN-γ, resulting in an antiparasitic mechanism in brain cells." (PMID 28000706, 2016). "The same patients, which developed ocular or cerebral toxoplasmosis had higher TNF-α levels than CHR individuals." (PMID 25352834, 2014). "On the other hand, the same patients, which developed ocular or cerebral toxoplasmosis had higher TNF-α levels than CHR individuals." (PMID 25352834, 2014). "The important role of TNF-α in parasite control was also confirmed by the observation that treatment with infliximab may lead to reactivation of cerebral toxoplasmosis." (PMID 30891027, 2019). "Thus, CD40−/− mice are susceptible to ocular and cerebral toxoplasmosis despite upregulation of key mediators of host protection: IFN-γ, TNF-α and NOS2." (PMID 21217818, 2010). "The increased levels of proinflammatory cytokines such TNF-α and IFN-γ during cerebral toxoplasmosis serves a role of controlling the parasite in the CNS." (PMID 35222377, 2022). "The major protective mechanisms of CD4+ and CD8+ T cells in cerebral toxoplasmosis are the production of protective cytokines, in particular IFN-γ and TNF." (PMID 30873157, 2019). "Together, these results demonstrate that increased parasite burden correlates inversely with the reduced levels of TNF, IFN-γ, IL-1 β, and IL-10 in brains of neutrophil-depleted mice with cerebral toxoplasmosis." (PMID 28680853, 2017). "IFN-γ, TNF-α and their downstream effector molecule NOS2 are considered the mediators of resistance against ocular and cerebral toxoplasmosis." (PMID 21217818, 2010). "Protection against ocular and cerebral toxoplasmosis in Saracatinib-treated mice was not the result of increased local expression of IFN-γ, TNF-α, IL-12 p40, and NOS2, mediators of resistance against ocular and cerebral toxoplasmosis." (PMID 39869638, 2025). "In parallel, we observed that Toxoplasma encephalitis, not impacted by sulfadiazine treatment, is correlated with an increased parasite burden and a lower expression of Th1-cytokine expression, especially IL-12, IFN-γ and TNF-α in the brain." (PMID 23374751, 2013).
endophthalmitis (13 papers, 2009 to 2024). An infectious process affecting the internal structures of the eye. "Scleral thinning due to scleritis is an additional possible mechanism that contributes to the increased risk of endophthalmitis during anti-TNF-α therapy and should be assessed." (PMID 32337619, 2020). "A specific endophthalmitis model in mice deficient for TNF-α with B. cereus resulted in reduced inflammation, more rapid bacterial replication, retinal function loss, and compensating proinflammatory cytokines." (PMID 22973073, 2012). "We previously reported that intraocular inflammation in TNFα-deficient mice was limited, resulting in a larger bacterial load and faster retinal function loss during endophthalmitis." (PMID 22163046, 2011). "In the vitreous of patients with distinct clinical characteristics, an intensified inflammatory response involving IL-10, IL-6, IL-8, IL-1β, and TNF-α was observed in cases of MDR P. aeruginosa endophthalmitis compared to infections caused by sensitive P. aeruginosa." (PMID 37624004, 2023). "To validate the role of identified immune mediators that were overexpressed in the pathogenesis of MDR-PA endophthalmitis, we analyzed the level of IL-6 and TNF-α by multiplex ELISA." (PMID 35046947, 2021). "The cytokine milieu in endophthalmitis was characterized by innate-related IL-6, tumor necrosis factor (TNF)-α, and IL-1β, which are involved in ocular barrier breakdown and leukocyte recruitment into ocular tissue." (PMID 34783307, 2021). "These range from a common conjunctivitis to endophthalmitis and can potentially be sight-threatening, highlightening the relevance of closely monitoring ocular manifestations in patients treated with anti-TNF-α agents." (PMID 32337619, 2020). "Our results demonstrated elevated expression of 16 mediators such as GCSF, GRO, IFN-γ, IL-1α, IL-1β, IL-1 RA, IL-6, IL-8, IP-10, MCP-1, MCP-3, MIP-1α, IL-1β, TGF-α, TNF-α in patients with culture positive endophthalmitis." (PMID 30296277, 2018). "Here, we demonstrate that SPA induces the production of pro-inflammatory mediators, including TNF-α, suggesting its role in promoting intraocular inflammation in endophthalmitis." (PMID 26053426, 2015). "In contrast, TNF-α level was significantly increased in the experimental Bacillus cereus endophthalmitis eyes." (PMID 19823583, 2009). "Moreover, cytokines such as interleukin (IL)-1, IL-6, IL-8, and tumor necrosis factor α, which can activate inflammatory cells in atherosclerotic plaque, have been found to be elevated during endophthalmitis." (PMID 36769859, 2023). "Furthermore, anti-TNF-α drug therapy may play a role in the migration of the intraocular cilium and the development of endophthalmitis." (PMID 23738990, 2013). "In an intradermal infection mice model, IL-1β, IL-6, TNF-α, and IFN-γ were produced by the lymph nodes only after MSSA infection; while in a murine model of endophthalmitis, IL-10, IL-15, IL-11, and some chemokines and receptors were significantly strongly upregulated by MRSA." (PMID 38571946, 2024). "While the role of certain immune mediators like tumor necrosis factor alpha (TNF-α) and interferon gamma (IFN-γ), have been studied in the development of endophthalmitis in animal models, very few expression studies have been carried out in humans suffering from infectious endophthalmitis." (PMID 30296277, 2018).